ABCB1 (ATP binding cassette subfamily B member 1)
Diseases named in the same sentence as ABCB1 in open-access papers (continued):
Sharing a sentence is not in itself a finding about the gene and the disease.
breast carcinoma (continued). "In a xenograft mouse model, silencing FTH1P3 was found to suppress the growth of paclitaxel-resistant breast cancer cells and decrease the expression of the ABCB1 protein." (PMID 41362671, 2026). "The cytotoxic effects of ibrutinib were enhanced in vitro by the presence of inhibitors targeting breast cancer resistance protein, encoded by ABCG2, and P-glycoprotein, P-gp, encoded by ABCB1." (PMID 40732285, 2025). "Previous research suggests that ERRγ interacts with p65 in breast cancer to regulate ABCB1 expression." (PMID 40918468, 2025). "A quantitative proteomic study of human brain metastases from lung and breast cancer patients found that P-gp/ABCB1 and BCRP/ABCG2 were undetectable in the microvessels of over 80% of samples when compared to the noncancerous cerebral cortex." (PMID 40806198, 2025). "For example, licochalcone A and flavokawain A reduced ABCB1 protein levels in BT-20 breast cancer cells and A549/T lung cancer cells, respectively." (PMID 40362377, 2025). "For example, STAT5A promotes doxorubicin resistance through transcriptional upregulation of ATP binding cassette subfamily B member 1 (ABCB1) in breast cancer." (PMID 40507264, 2025). "For instance, a trastuzumab-conjugated liposomal formulation was engineered to co-encapsulate paclitaxel and anti-ABCB1 siRNA, to enhance cytotoxicity against HER2-positive breast cancer cells by silencing ABCB1, the gene encoding P-gp." (PMID 40867257, 2025). "Repeated treatment with the ADC N41mab-vcMMAE, which targets nectin-4 and has MMAE as its payload, in mice xenografted with the SUM190 breast cancer cell line induced refractory tumors which were found to overexpress ABCB1 as the mechanism of resistance." (PMID 40501953, 2025). "The aberrant activity of the Ras/MAPK pathway has been identified as pivotal in the initiation and progression of breast cancer, miR‐21's targeting of key activators within this pathway, including ABCB1, AR, CDK6, CSF1, EREG, MKDR, among others." (PMID 40567015, 2025). "For breast cancer, miR-483-3p and miR-138-5p showed favorable predictions against ABCB1/PTP4A2 and TMBIM6, respectively, while miR-365 and miR-331-3p mapped to ABCG2/AP2M1." (PMID 41378310, 2025). "SNPs near genes such as CACNB4, STAM2, and ABCB1 are associated with a higher risk of CIA, particularly in breast cancer cohorts." (PMID 40227705, 2025). "For example, circABCB1, derived from the ABCB1 gene, has been shown to diminish sensitivity to docetaxel in breast cancer, presumably by sponging miRNAs that would normally downregulate ABCB1, thereby indirectly maintaining high P-gp levels." (PMID 40806254, 2025). "Along with our observation, upregulation of ABC transporters, including ABCB1, in Doxorubicin-resistant breast cancer cells, emphasizing the conserved role of these transporters in CSC-mediated resistance." (PMID 40251609, 2025). "A retrospective cohort study of 105 Taiwanese breast cancer patients treated with palbociclib, a targeted CDK4/6 inhibitor, examined the prevalence of neutropenia associated with four SNPs: ABCB1_rs1045642, ABCB1_rs1128503, ERCC1_rs3212986, and ERCC1_rs11615." (PMID 40227705, 2025). "Among the frequently overexpressed members of ATP-ABC, MDR-associated protein-1 (MRP1/ABCC1), breast cancer resistance proteins (ABCG2), and P-glycoprotein (P-gp/ABCB1) are notable." (PMID 38715021, 2024). "In a cell culture study, a doxorubicin-resistant breast cancer cell model (MCF-7/ADR) was also found to express significantly higher levels of ABCB1 but lower levels of GAS5 than the drug-sensitive MCF-7 parental cells." (PMID 39403602, 2024). "In conclusion, our study underscores the potential of siRNA-based therapies, particularly in combination with vinorelbine, in overcoming drug resistance in breast cancer cells with elevated ABCB1 expression." (PMID 39206391, 2024).
breast carcinoma (continued). "Overexpression of ABCB1 was documented after doxorubicin treatment in a genetically engineered mouse model (GEMM) of breast cancer, resulting in MDR including DTX." (PMID 39090086, 2024). "Studies have indicated that overexpression of GAS5 enhances ADR sensitivity, induces cell apoptosis, and inhibits the function of ABCB1, offering the potential to overcome chemotherapy resistance in breast cancer patients." (PMID 40125243, 2024). "In particular, eribulin induced an acquired resistance in breast cancer cells by inducing an overexpression of ABCB1 and ABCC11 genes." (PMID 38534323, 2024). "The results of the present study indicate that the concurrent use of siRNA and vinorelbine holds substantial promise as a therapeutic approach to overcome ABCB1-mediated multidrug resistance (MDR) in breast cancer." (PMID 39206391, 2024). "Elevated ABCB1 expression is associated with MDR in several cancers, including acute myelogenous leukemia, breast cancer, and lung cancer, making it a potential prognostic marker and target for modulators." (PMID 38397468, 2024). "ATF3 elevation, in turn, stimulates increased expression of ABCB1 efflux pumps resulting in enhanced tamoxifen efflux conferring the breast cancer cells' resistance to this drug." (PMID 39661414, 2024). "This combination therapy holds promise as a therapeutic approach to combat ABCB1-mediated MDR in breast cancer." (PMID 39206391, 2024). "In breast cancer cells, miR-381 downregulates the drug transporter protein ABCB1/MDR1, which influences cisplatin sensitivity." (PMID 38172984, 2024). "RNA sequencing analysis has revealed the downregulation of GAS5 and upregulation of ABCB1 in ADR-resistant breast cancer tissues and cells." (PMID 40125243, 2024). "Here, we assessed that ABCB1 (P-glycoprotein) expression is strongly increased (log2FC = +5.301, about 40 times more) and it is known to be responsible for the eribulin resistance of many breast cancer cell lines, including the MDA-MB-231 used in this study." (PMID 38534323, 2024). "STAT5 has been identified as a key promoter in Dox resistance in breast cancer by positively regulating ABCB1 expression; in our study, we also observed positive regulation of ABC transporters." (PMID 39180549, 2024). "In breast cancer, one of the most common causes of clinical resistance to doxorubicin is overexpression of ABC efflux transporters, such as P‐glycoprotein (P‐gp)/ABCB1." (PMID 36880347, 2023). "Our results indicate that ABCB1 mRNA and p-GP expression are significantly increased in breast cancer MCF-7 / Taxol cells." (PMID 36867605, 2023). "In contrast, the lncRNA FTH1P3 induced paclitaxel resistance in breast cancer cells by targeting the miR-206/ABCB1 axis to increase ABCB1 protein production." (PMID 37569629, 2023). "In that model system, the multidrug resistance of MCF-7/KCR breast cancer cells was acquired, as it was the result of increasing Doxorubicin concentration pressure and the consequent overexpression of ABCB1." (PMID 36839907, 2023). "Others such as perifosine, BEZ235, and DHW-211 have been reported to reverse drug resistance in ABCB1-overexpressing breast cancer, ovarian cancer, and NSCLC cell lines, respectively." (PMID 37048130, 2023). "These two studies provide evidence that, at least in ovarian and breast cancer, ABCB1 gene fusions that retain exon 2 onwards lead to the upregulation of P-gp and are responsible for acquired chemotherapy resistance." (PMID 37686513, 2023). "Overexpression of cell surface efflux ABC transporters, including ABCB1, ABCC1, and ABCG2, was associated with chemoresistance in breast cancer." (PMID 37397367, 2023). "In contrast to ABCB1, ABCG2 protein and mRNA expression has been demonstrated in breast cancer, and can be linked to therapy response." (PMID 37147730, 2023).
breast carcinoma (continued). "It is, therefore, interesting that ABCB1-overexpressing, doxorubicin-resistant canine mammary cancer and human osteosarcoma cells relied on multiple resistance mechanisms, as they also showed cross-resistance to platinum-based agents." (PMID 37175843, 2023). "Our previous study showed that changes in the expression levels of several ABC genes (ABCB1, ABCC1, ABCC2, ABCC5, ABCG1, and ABCG2) during neoadjuvant chemotherapy (NAC) were associated with the response to this therapy in breast cancer patients." (PMID 35631534, 2022). "In contrast to the breast cancer cell lines, a moderate increase of ABCB1 and MRP-1 and -5 was observed in Tx-R GIST cells when compared with their parental GIST T-1 cells." (PMID 35327403, 2022). "For this purpose, we used the Calcein AM, a well-known fluorescent ABCB1 substrate, and examined its expression in resistant breast cancer cells after BGJ 398 treatment." (PMID 35327403, 2022). "A recent gene expression study, analyzing breast cancer tumors pre- and post-neoadjuvant anthracycline and taxane-based treatment, showed that ABCB1 expression is induced primarily upon treatment." (PMID 35721223, 2022). "Consistently, a study confirmed that enzymes including CYP1A1, CYP2C19, ABCB1, and other key transporters involved in drug resistance were significantly upregulated in the anthracycline-R breast cancer cell lines." (PMID 36551262, 2022). "The carcinogenic effect of ABCB1 has also been demonstrated in animal models of breast cancer and liver cancer." (PMID 35965433, 2022). "conjugated both ABCG2 and ABCB1 sequences onto pH-sensitive carbonate apatite nanoparticles for dual siRNA-mediated targeting of human breast cancer cell lines (MCF-7)." (PMID 36153528, 2022). "Similar to its effects on ABCC4 mRNA, miR-381-3p targets the 3′UTR of ABCB1 mRNA and promotes cisplatin sensitivity in breast cancer cells This suggests that miR-381-3p is involved in the posttranscriptional regulation of other xenobiotic transporters." (PMID 35753353, 2022). "It is potentially implicated in breast cancer MDR, but the extent to which ABCB1 alters chemoresistance is controversial and likely dependent on its expression." (PMID 33801148, 2021). "Here we identified STAT5a as a chemoresistance inducer that regulates the expression of ABCB1 in breast cancer and can be targeted by pimozide, an FDA-approved psychotropic drug." (PMID 34336684, 2021). "In chronic myeloid leukemia (CML) cells, GCS can increase the expression of ABCB1 through NF-κβ signaling, a different mechanism than the one described in breast cancer." (PMID 35004331, 2021). "The results of our study showed that STAT5a was overexpressed and persistently activated in a chemoresistant breast cancer cell line and upregulated ABCB1 expression by promoting its transcription." (PMID 34336684, 2021). "The occurrence of different fusions involving the ABCB1 gene, which encodes multidrug resistance protein 1 (MDR1), was observed in post-treatment high-grade serous ovarian cancer (HGSC) and end-stage breast cancer samples." (PMID 34503137, 2021). "The roles of STAT5a and ABCB1 in chemoresistance in breast cancer and their regulation were further confirmed by IHC analysis of breast cancer tissues from 67 patients who received DOX-containing neoadjuvant treatment." (PMID 34336684, 2021). "A comprehensive analysis of ABCB1 expression in more specific breast cancer subsets is required to expand the current knowledge about its role in breast cancers." (PMID 33801148, 2021). "We found that STAT5a- or ABCB1-expressing patients exhibited a significantly lower pCR rate, implying the vital roles of STAT5a and ABCB1 in chemoresistance in breast cancer." (PMID 34336684, 2021). "Attenuation of ABCB1 reduced the migratory capacity of both MCF-7 breast carcinoma and rat brain endothelial cells, with overexpression associated with increased migration." (PMID 34830797, 2021).
breast carcinoma (continued). "The overexpression of ABCB1 has been correlated with chemoresistance in many cancer cell lines, such as kidney, colon, adrenal, pancreas, liver and breast cancers." (PMID 33801148, 2021). "Exosomes derived from doxorubicin-resistant breast cancer cell lines induce drug resistance to sensitive cells and this occurs by exosomal transfer of ABCB1 from resistant cells to sensitive ones." (PMID 33920605, 2021). "The SNPs rs1045642, rs1128503 and rs2032582 in ABCB1 were found to contribute to the altered pharmacokinetics of doxorubicin in Asian breast cancer patients." (PMID 33801148, 2021). "Then, we confirmed the essential roles of STAT5a and ABCB1 in doxorubicin resistance in breast cancer cells and the regulation of ABCB1 transcription by STAT5a." (PMID 34336684, 2021). "For example, Hertz and Caram reported that ABCB1 SNP rs1045642 3435C>T displayed a cardioprotective effect in a study of 166 breast cancer patients treated with doxorubicin." (PMID 33801148, 2021). "We verified the function of ABCB1 in chemoresistance in breast cancer cells in our study and proved its regulation by STAT5a." (PMID 34336684, 2021). "Here, we identified STAT5a as a key promoter of doxorubicin (DOX) resistance in breast cancer via upregulation of the expression of ABCB1." (PMID 34336684, 2021). "It has been demonstrated that ABCB1 expression is ~200% higher in breast cancer tissue compared to normal breast tissue even prior to chemotherapy." (PMID 35070633, 2021). "UCH-L1 enhances multidrug resistance and upregulates ABCB1 expression via activation of the mitogen-activated protein kinase/extracellular receptor kinase MAPK/ERK signaling pathway in human breast cancer cells." (PMID 33920605, 2021). "Taken together, these results suggested that STAT5a conferred DOX resistance to breast cancer cells by regulating the transcription of ABCB1." (PMID 34336684, 2021). "First, the level of ABCB1 was significantly higher in tumor tissues from patients with chemoresistant breast cancer than in those from chemosensitive patients." (PMID 34336684, 2021). "Apart from ABCB1 and ABCG2, some other ABC transporters are also implicated in breast cancer metastasis." (PMID 33801148, 2021). "For instance, miR-451 and miR-326 are required for the chemosensitivity of breast cancer cells to doxorubicin via direct targeting of ABC family transporter genes ABCB1 and ABCC1 (MRP1), respectively." (PMID 32345117, 2020). "Six studies have determined DNA methylation levels of ABCB1 in clinical samples from breast cancer patients." (PMID 33066132, 2020). "ABCC11 expression (together with ABCB1) is responsible for resistant phenotype of breast cancer cell lines resistant to eribulin and inhibition of ABCC11 can partially restore the cross-resistance to 5-fluorouracil." (PMID 33334016, 2020). "We then tested its ability to detect ABCB1-mediated MDR in vivo by measuring its uptake in an orthotopic model of chemotherapy-resistant breast cancer expressing clinically relevant levels of ABCB1." (PMID 31729540, 2020). "Elizabeth and colleagues detected frequent transcriptional fusions of ABCB1 increasing substrate chemotherapy sensitivity in relapsed breast cancer." (PMID 33324554, 2020). "Similar associations of ABCB1 with favourable OS have been reported in two of these cancers (HNSC, PAAD), and also in breast cancer (BRCA) and kidney cancer (KIRC)." (PMID 33202946, 2020). "In a follow-up study, the DNA methylation status of 12 candidate genes including ABCB1 has been determined in 238 breast cancer tissue samples from early premalignant DCIS to advanced metastatic breast cancer." (PMID 33066132, 2020). "ABCB1 and ABCC3 proteins, members of ATP binding cassette (ABC) transporter family, are associated with chemoresistance in breast cancer cells." (PMID 32947901, 2020). "The ABCB1 gene is commonly demonstrated to be upregulated after chemotherapy due to chromosomal translocations in ovarian and breast cancers." (PMID 33324554, 2020).
breast carcinoma (continued). "To establish a potential mechanism of ROR1 regulation of drug efficacy in breast cancer cells, we investigated the multi-drug efflux pump ABCB1 after ROR1 inhibition." (PMID 32020017, 2020). "In the same manuscript, three N-alkylated 3-aminochalcones were also synthesized and discussed for their ability to selectively inhibit P-glycoprotein (Pgp; ABCB1) and breast cancer-resistant protein (BCRP; ABCG2)." (PMID 33213087, 2020). "According to data analysed by Oncomine, mucinous breast carcinoma was the only breast tumour that had high expression of PTGS2, EGFR, and ABCB1, suggesting that expression of these genes vary based on breast cancer type." (PMID 32577155, 2020). "A proposed method to selectively target ABCB1 and chemoresistance in breast cancer has been to target cancer-specific upstream regulators of ABCB1, minimizing any detrimental effects to normal tissue." (PMID 32020017, 2020). "On ABCB1 over-expressing and Dox resistant human breast cancer MCF-7/dox cells, Quercetin significantly enhances the antitumor activity of Dox, paclitaxel, and vincristine." (PMID 31245292, 2019). "In the present study, the modulating effect of miR-203 and miR-200c on the activity of efflux pumps in DOX resistant breast cancer cells that constitutively over-express ABCB1 efflux pumps, was investigated." (PMID 35582584, 2019). "Instead, they used a doxorubicin-resistant breast cancer cell line (MCF7/ADR) to prove that miR-200c regulates ABCB1 by directly targeting its 3’-UTR." (PMID 35582590, 2019). "The purpose of this study was to functionally assess the regulation of ABCB1 activity in a doxorubicin-resistant breast cancer cell line by miR-200c and miR-203." (PMID 35582584, 2019). "In the present study, single nucleotide polymorphisms (SNPs) from the ABCC1, ABCC2, ABCB1, and ABCG2 genes were screened in breast cancer patients and healthy volunteers from the Jordanian-Arab population." (PMID 31391850, 2019). "The combined treatment of Dox, paclitaxel, and vincristine with Quercetin significantly down-regulates ABCB1 expression and eliminates breast cancer stem cells." (PMID 31245292, 2019). "Their results showed that miR-381 was down-regulated in cisplatin resistant breast cancer tissues and cell lines, and ABCB1 expression is inversely correlated." (PMID 35582590, 2019). "An ABCB1 fusion involving NRF1 was found in Patient 14 that co-occurred with an SLC25A40–ABCB1 fusion, demonstrating that convergent ABCB1 deregulation also occurs in breast cancer patients." (PMID 30894541, 2019). "ABCB1 polymorphism was associated with risk of recurrence or disease free survival (DFS), in breast cancer patients on tamoxifen treatment." (PMID 31547390, 2019). "As expected, PYGO2 inhibition restored drug sensitivity in MDR cells by decreasing ABCB1 expression, reducing the breast cancer stem cell subset following chemotherapy." (PMID 31921125, 2019). "For example, lncRNA FTH1P3 promotes ATP binding cassette subfamily B member 1 (ABCB1) protein expression by targeting miR-206, acting as a miRNA “sponge,” leading to the activation of paclitaxel resistance in breast cancer." (PMID 31456943, 2019). "It was found that 500-kDa HA stimulated ABCB1 expression via CD44 in breast cancer (MCF-7 cells), inducing resistance to doxorubicin, paclitaxel, and etoposide." (PMID 31443261, 2019). "The regulation of FOSL2 in the context of breast cancer and ABCB1 in the context of ovarian cancer by miR-143-5p is yet to be studied." (PMID 31245295, 2019). "Taken together, our results illuminate the FTH1P3/miR‐206/ABCB1 pathway in the chemoresistance of breast cancer." (PMID 29971911, 2018). "This exploratory study aimed to investigate the interplay between preoperative statin use, the ABCB1 C3435T polymorphism, and tumor-specific HMGCR expression in relation to breast cancer-free and distant metastasis-free intervals and overall survival." (PMID 30370250, 2018).